CD151 (CD151 molecule (Raph blood group))
Diseases named in the same sentence as CD151 in open-access papers (continued):
Sharing a sentence is not in itself a finding about the gene and the disease.
tumor (continued). "In contrast, CD151 disruption markedly blunts survival of epithelial basal cell-derived tumor cells, consistent with the impact of CD151 knockdown on MDA-MB-231 cells." (PMID 33919420, 2021). "The role of CD151 and other tetraspanins during tumor growth and progression has long been postulated to be manifested through regulation of tumor cell adhesion, survival, migration, and invasion in an integrin-dependent manner." (PMID 33919420, 2021). "CD151 regulated laminin-binding integrins and control tumor cell migration and invasion through its effect on their adhesive and signaling functions." (PMID 34108040, 2021). "Other recent studies regarding CD151 expression revealed that its level is correlated with tumor neovascularization, with the tetraspanin’s levels being directly connected to the angiogenesis process of neoplastic tissue." (PMID 34830819, 2021). "Luminescence decreased in the HCT116 sh-CD151 group indicating that tumor progression was repressed by reducing CD151 expression." (PMID 33767593, 2021). "CD151 is one such prominent member of the tetraspanin family recently suggested to mediate tumor development, growth, and progression in oncogenic context- and cell lineage-dependent manners." (PMID 33919420, 2021). "Tumor growth was significantly slower in the sh-CD151 groups compared with the control groups, with reduced tumor volumes and weights." (PMID 33767593, 2021). "To this end, we detected the expression of CD151 in tumor tissues and its paired adjacent tissues, and then analyzed its correlation with prognosis and pathological parameters." (PMID 34108040, 2021). "Here, we addressed the pro-tumoral role of CD151 in NSCLC by targeting EGFR/ErbB2 which favors tumor proliferation, migration and invasion." (PMID 34108040, 2021). "CD151 is involved in cell-to-cell communication, wound healing, platelet aggregation, cell trafficking and tumor progression." (PMID 34108040, 2021). "Increased expression of CD151 in vitro leads to high tumor cell invasion and proliferation, while low levels are associated with inhibition of these cellular processes." (PMID 34830819, 2021). "On the other hand, overexpression of CD151 promoted tumor growth as evidenced by increased tumor volume and tumor weight." (PMID 34108040, 2021). "The involvement of CD151 due to impaired tumor-endothelial interactions was also demonstrated in CD151-knockout mice." (PMID 34108040, 2021). "In GBM, CD151 associates with α3β1 integrin to potentiate EGFR signaling, drive cancer cell motility and tumor aggressiveness." (PMID 32616845, 2020). "To test this, we performed an identical CRISPR screen in vitro, where ITGB1, FERMT1, and CD151 proved less important for tumor growth than in vivo." (PMID 32579974, 2020). "In spontaneous lung metastasis models, CD151-null mice exhibited a marked delay in tumor initiation and a decrease in number of metastastic lesions." (PMID 32117989, 2020). "In the context of cancer, both experimental lung metastasis and tumor cell residence were reduced in CD151-null mice." (PMID 32117989, 2020). "Given the close association of CD151 with oncogenic drivers including growth factors, such as EGFR, HER2, and HGFR (c-Met), CD151 was shown to impair growth factor receptor-dependent processes such as tumor onset, cell growth, spreading and motility." (PMID 32117989, 2020). "Still, metastasis of PaCa cells transplanted into either TSPAN8−/− or TSPAN8−/−/CD151−/− mice is effectively inhibited, suggesting that host Tspan8 or CD151 can significantly affect tumor progression." (PMID 32878635, 2020). "The observed hyper-responsive phenotype of CD151+ T cells is in line with reports that describe CD151 as a marker of tumor aggressiveness and the reported role of CD151 in TCR/CD3 signaling." (PMID 32978478, 2020). "Previous studies have shown that CD151 is overexpressed in multiple tumors and participates in tumor progression." (PMID 32381016, 2020).
tumor (continued). "CD151 interacts with laminin-binding integrins and growth factor receptors, and is reported in cancer-promoting processes such as tumor initiation, metastasis, and angiogenesis." (PMID 32117989, 2020). "Immunoreactivity of CD151 protein was located on the cell membranes and its intensity in tumor tissues was stronger than that in paratumoral tissues." (PMID 31772652, 2019). "As described in our previous study, high level of CD151 was significantly related to tumor size (>5cm) (p=0.007) and vascular invasion (p=0.003)." (PMID 31772652, 2019). "More importantly, HCC patients with CD151 overexpression had poor prognosis, to a large extent, depending on high Mortalin expression in tumor tissues." (PMID 31772652, 2019). "Anti-CD151 antibodies inhibited metastasis spread and primary tumor growth in human tumor mouse models." (PMID 30769765, 2019). "Results were seen in multiple tumor cell lines, in which CD151 was either knocked down (using shRNA/RNAi) or knocked out (for the first time using CRISPR/Cas9)." (PMID 30778617, 2019). "Targeted ablation of tetraspanin protein CD151 sensitized tumor cells to a variety of anti-cancer drugs." (PMID 30778617, 2019). "For example, the tetraspanin CD82 is downregulated during metastases, while the tetraspanin CD151 and tetraspanin 8 are induced and able to support tumor progression." (PMID 31437164, 2019). "High expression of CD151 gene and protein has been detected in tumour tissues from breast, colorectal, hepatocellular, lung, pancreatic and prostate cancer patients." (PMID 29568359, 2018). "Studies on human tumor cells reported associations between tetraspanin expression and tumor progression showing both reduced (CD82, CD9) and increased expression (CD151, Tspan8) in various cancer types." (PMID 29896201, 2018). "This suggests that RNASEH2A and CD151 have compensatory roles in promoting cell cycle progression and tumor growth." (PMID 29843367, 2018). "CD151, as one of the most important members of the tetraspanin family, has been found high expressed in numerous neoplasms." (PMID 29568359, 2018). "In contrast to CDK1 knockdown, transfection of RCC cell lines with either si-RNASEH2A or si-CD151 resulted in impaired tumor proliferation." (PMID 29843367, 2018). "A recent study showed that expression of CD151 in human is associated with a hyper-proliferative T cell phenotype, it would be interesting to know if CD151 expressed in mouse immune cells plays a role in tumor progression." (PMID 29946318, 2018). "In summary, our results indicated that CD151 is upregulated in RCC and high level of CD151 is associated with advanced tumor stage and poor survival significantly." (PMID 29568359, 2018). "As the first identified member of the tetraspanin family, CD151 was shown to participate in tumor cell behaviors, including cell growth, proliferation, motility and invasiveness, possibly via interacting with a number of different proteins." (PMID 27888619, 2017). "In the web of tetraspanins, CD151 and Tspan8 have high relevance for tumor progression and modulation of the tumor microenvironment." (PMID 28098821, 2017). "CD151 was highly expressed in endothelial cells of the hepatic sinusoids and neovessels developing in fibrotic septa and tumor margins." (PMID 28473332, 2017). "There is evidence that CD151 regulates tumor cell adhesion, migration and invasion/intravasation, and dissemination." (PMID 28752248, 2017). "This is apparent in Cd151-/- mice that are impaired in wound healing, and are protected against tumor cell metastasis." (PMID 28880937, 2017). "Existing evidences have also shown that CD151 expression is also important for tumor neoangiogenesis and epithelial-tomesenchymal transition." (PMID 27888619, 2017). "Immunofluorescent staining of HCCLM3 cells using the CD151 mAb 9B revealed that CD151 is expressed in the plasma membrane of tumor cells." (PMID 26756217, 2016).
tumor (continued). "To further investigate the role of CD151 mAb 9B in vivo, we used a subcutaneous metastasis model to assay its impact on the efficiency of tumor growth and progression." (PMID 26756217, 2016). "As an oncogene, CD151 not only supports growth of various types of tumors but also regulates tumor cell spreading, migration and invasion and facilitates metastatic process." (PMID 27270320, 2016). "The results also showed that the immunoreactivity of CD151 was localized to the plasma membrane of the tumor cells and that the intensity of CD151 immunoreactivity in the HCC tissues was stronger than that in the paratumoral samples (p<0.01)." (PMID 26756217, 2016). "An in vivo assay showed that CD151 mAb 9B inhibited tumor growth potential and HCC cells metastasis." (PMID 26756217, 2016). "We successfully produced a CD151 mAb 9B targeting the CD151/integrin α6β1-binding domain, which not only can displayed good reactivity to the CD151 antigen but also prevented tumor progression in HCC." (PMID 26756217, 2016). "Next, a transwell assay was used to investigate the role of CD151 mAb 9B in the invasiveness of tumor cells." (PMID 26756217, 2016). "To determine the bioactivity of CD151 mAb 9B, we performed an in vitro cell migration assay to assess its role in the mobility of tumor cells." (PMID 26756217, 2016). "The surface protein CD151 was equally positive on fibroblasts and tumor cells as indicated by immunostaining." (PMID 25885552, 2015). "Disruption of CD151 or α3β1 integrin markedly impairs EGF/EGFR-evoked tumor cell motility and invasiveness." (PMID 26377974, 2015). "Based on this finding, the known contribution of exosomes to the metastatic process and the functional importance of exosomal tetraspanins, we controlled for the contribution of exosomal CD151 and Tspan8 in tumor progression." (PMID 25544774, 2015). "CD151 staining was primarily localized on the plasma membrane of tumor cells and detectable in the cytoplasm." (PMID 26377974, 2015). "Except in rats receiving ASMLwt exosomes, tumor cells were hardly recovered particularly in lung and BM, indicating that both exosomal Tspan8 and CD151 contribute to niche preparation." (PMID 25544774, 2015). "In the three cell lines most sensitive to EGF (LN229, LN308, and LN428), CD151 knockdown led to a 2- to 7-fold decrease in the number of tumor cells invading through the Matrigel after EGF stimulation." (PMID 26377974, 2015). "CD151 is known to be a promoter of metastasis and several antibodies targeting this tetraspanin have been reported to inhibit tumour spread, motility and invasion in vitro and in vivo." (PMID 24662676, 2014). "Mechanistically, CD151 conveys its tumor-suppressing function largely by stabilizing α3β1 integrin- and E-cadherin-mediated cell-cell contact, while counteracting the EMT-like process through repressing the activation of Slug and canonical Wnt signaling." (PMID 25356755, 2014). "For instance, CD151 has been suggested to promote tumor cell invasiveness and drug sensitivity through regulation of α6 integrins (α6β1 and α6β4)." (PMID 25356755, 2014). "Some tetraspanins including CD9, CD82 and CD63 are considered to be tumour suppressors whereas others such as CD151 and CO-029 promote metastasis." (PMID 24662676, 2014). "In this study, we found that deletion of Cd151 significantly impaired tumor development and progression in the murine MMTV/PyMT breast tumorigenesis model." (PMID 25012362, 2014). "TM4SF5 interacted with CD151, and caused the internalization of CD63 from the cell surface into late lysosomal membranes, presumably leading to terminating the tumor-suppressive functions of CD63." (PMID 25033048, 2014). "It would be interesting to evaluate separately the specific effect of Cd151 deletion in the stroma (tumor vasculature, immune cells, myoepithelial cells) and the luminal epithelium/tumor cells respectively, using a conditional knock-out model." (PMID 25012362, 2014).
tumor (continued). "Of interest is the inhibition by CD151 antibodies of tumor cell intravasation and metastasis formation in the chick embryo." (PMID 25285080, 2014). "While there was a trend towards delayed tumor onset in Cd151−/− PyMT mice compared to Cd151+/+ PyMT littermate controls, this result was only approaching significance (Log-rank test P-value =0.0536)." (PMID 25012362, 2014). "There was however a trend towards increased tumor latency in Cd151−/− (T50 = 67 days; n = 25) as compared to Cd151+/+ (T50 = 61.5 days; n = 26) that was approaching significance (Log-rank test P-value =0.0536)." (PMID 25012362, 2014). "In contrast, significant CD151 staining was detected on the plasma membrane of tumor cells, and displayed a wide range of intensities between tumor tissue samples." (PMID 25356755, 2014). "In tumor xenograft model, CD-151 knockdown cells showed reduced tumorigenecity compared to normal tumor cells." (PMID 23586059, 2013). "Univariate analysis showed that tumor size, depth of invasion, lymph node involvement, high tumor stage, high CD151 expression, high level of integrin α3 and co-expression of CD151 and integrin α3 were predictors for OS." (PMID 23533596, 2013). "In tumor tissues, CD151 expression showed considerable heterogeneity in the different samples (Figs. 4a1, b1, c1 and d1)." (PMID 23533596, 2013). "The tetraspanin superfamily proteins (TM4SF) mainly CD9, CD63, CD82, CD151 and CD81 have been implicated in cell migration, proliferation and tumor cell metastasis." (PMID 23128478, 2013). "Apart from CD151, the tetraspanin TSPAN8 (previously known as CO-029, TM4SF3) has been also associated with tumor progression." (PMID 24350713, 2013). "Immunohistochemical staining of EOC tumors and normal ovary showed CD151 expression in tumor cells as well as normal OSE cells." (PMID 22272937, 2012). "CD151-blocking antibody was reported to inhibit invasion and intravasation at the site of the primary tumour." (PMID 22294188, 2012). "The ability of CD151 to affect cell dissociation and migration in other tumor models and our novel discovery of its expression in EOC made CD151 a good proof-of-principle candidate for further study." (PMID 22272937, 2012). "Although tetraspanins CD82 and CD9 are known to suppress metastasis, CD151 promotes metastasis by regulating tumour cell migration." (PMID 22294188, 2012). "CD151 overexpression occurred mainly in the membrane and/or cytoplasm in the tumour cells of the cases." (PMID 22294188, 2012). "In xenograft tumor models, antibody-mediated inhibition of CD151 has been shown to hinder the spread of metastatic tumors, reinforcing the idea that CD151 is functionally important for either cell detachment from a tumor or migration away from that tumor." (PMID 22272937, 2012). "We then confirmed expression of CD151 in this discovery set and a second set of tumor tissues using qRT-PCR and immunohistochemistry." (PMID 22272937, 2012). "Tumor volumes of CD151-HepG2-derived xenografts were 1.89±0.6 cm3, which were significantly larger than those of HepG2-CD151-shRNA-CD151 and HepG2-CD151-shRNA- integrin β1 (0.51±0.05 cm3 and 0.47±0.04 cm3, respectively, P<0.01)." (PMID 21961047, 2011). "Previously, we determined that CD151 was a crucial molecule involved in tumor cell invasion, tumor neo-angiogenesis, and epithelial-mesenchymal transition (EMT)." (PMID 21961047, 2011). "Increased expression of CD151 also correlates with advanced tumour grades and poor prognosis in other tumours." (PMID 21505452, 2011). "The truncated form of CD9P-1, GS-168AT2, potently inhibits angiogenesis and cell migration by at least the downregulation of CD151 and CD9, which provides the first evidences for the central role of CD9P-1 in tumour-associated angiogenesis and tumour growth." (PMID 21863033, 2011). "Expression of CD151 was highest in ‘triple-negative’ tumours as compared with the rest of the cohort (P<0.001)." (PMID 21505452, 2011).
tumor (continued). "Tetraspanins are small transmembrane proteins, such as CD9, CD37, CD53, CD63, CD81, CD82, CD151 and tetraspanin 8, that are involved in a multitude of biological processes, including cell-cell adhesion, metastasis suppression and tumour progression." (PMID 21339979, 2010). "CD151 and tetraspanin 8 support tumour progression; increased CD151 is an indicator of poor prognosis." (PMID 21339979, 2010). "To assess the influence of CD151 on in vivo tumor growth, we employed two murine tumor models." (PMID 38840183, 2024). "Our study is the first to demonstrate a strong association between CD151 expression and the status of EGFR mutation, specifically noting a higher prevalence of CD151 expression in tumours lacking these mutations." (PMID 38982031, 2024). "Specifically, high CD151 expression was observed in 77% of patients whose tumours did not have EGFR mutations." (PMID 38982031, 2024). "This specific type of tumour, characterised by high CD151 and the absence of EGFR mutations, was associated with poorer survival outcomes in patients from both our study cohorts." (PMID 38982031, 2024). "Tumor exosomes display Tspan8 and CD151 that stimulate angiogenesis and tumor progression." (PMID 37108809, 2023). "Furthermore, subunit α6 was detected in neutrophils and CD151 was observed in tumor cells using the dual-color IHC assays for lymphatic cancer emboli." (PMID 37056931, 2023). "In conclusion, CD151 induces distant cancer cell metastasis by regulating tumor cell motility." (PMID 35747825, 2022). "Furthermore, we examined the efficacy of myriocin in preventing CD151 high-expression tumor progression in vivo." (PMID 36209197, 2022). "The tetraspanin CD151 was the first tetraspanin to be identified as a tumour promoter." (PMID 35597804, 2022). "Importantly, myriocin selectively restrained CD151-high expression tumor growth in preclinical patient-derived xenograft models." (PMID 36209197, 2022). "However, in ovarian cancer and invasive lobular breast cancer, CD151 can bind to integrin α3β1 to regulate signaling pathways downstream of this complex, ultimately impairing tumor progression." (PMID 35280793, 2022). "The main functions of CD151 are to maintain the integrity of epithelial cells, platelet aggregation, regulation of membrane fusion, cell motility, and participation in angiogenesis and tumor metastasis." (PMID 36613908, 2022). "The tumor weight and tumor volume were both decreased in CD151 knockdown group." (PMID 34108040, 2021). "Indeed, a number of studies have shown that significant overexpression of CD151 is related to tumor cell motility, adhesion, proliferation and metastasis 6-8." (PMID 33767593, 2021). "Additionally, CD151 and CD9 are tightly associated with activities of tumor-initiating cells or CSCs." (PMID 33919420, 2021). "Additionally, the presence of CD151 in exosomes derived from tumors or their microenvironments suggests a new mechanism for its role in tumor relapse and drug resistance." (PMID 33919420, 2021). "In contrast, the tetraspanin protein CD151 on some sEVs has a role in promoting tumor growth." (PMID 34094979, 2021). "Besides, inoculation of nude mice with CD151-overexpressing tumor cells exhibited substantial tumor proliferation compared to that in control mice which inoculated with vector-transfected tumor cells." (PMID 34108040, 2021). "Tspan8/CD151 exosomes contribute to tumour progression by stimulating angiogenesis in vivo." (PMID 34671031, 2021). "However, several reports have indicated that CD151 expression depends on the stage of tumor progression 10-12." (PMID 33767593, 2021). "Additionally, the process of proteolysis and enabled signaling, which is CD151 dependent, is likely to promote tumor progression." (PMID 34830819, 2021). "Tspan8 and CD151 tetraspanins have been shown to contribute to tumor progression." (PMID 33773551, 2021).